CLMAT3 (colorectal liver metastasis associated transcript 3)
Synonyms: SPARC-AS1; CTB-113P19.1
Gene: Long non-coding RNA gene on chromosome 5 (151,676,945 to 151,725,475, forward strand). Ensembl gene ENSG00000249035.
Diseases named in the same sentence as CLMAT3 in open-access papers:
CLMAT3 is named in the same sentence as 2 diseases in open-access papers, as found by Europe PMC text mining. Sharing a sentence is not in itself a finding about the gene and the disease. The quoted sentences say what the papers report.
colorectal cancer (2 papers, 2016 to 2017). A primary or metastatic malignant neoplasm that affects the colon or rectum. "Over-expression of long non-coding RNA (lncRNA)-CLMAT3 is significantly associated with colorectal liver metastasis and is an independent predictor of poor survival for colorectal cancer patients." (PMID 27391344, 2016).
CLMAT3 also shares sentences with these, for which no sentence is quoted: tumor (1 paper).